CXCR5 (C-X-C motif chemokine receptor 5)
Diseases named in the same sentence as CXCR5 in open-access papers (continued):
Sharing a sentence is not in itself a finding about the gene and the disease.
Hodgkins lymphoma (2 papers, 2021 to 2023). A heterogeneous group of malignant lymphoid neoplasms of B-cell origin characterized histologically by the presence of Hodgkin and Reed-Sternberg (HRS) cells in the vast majority of cases. "A similar rate of CXCR5 expression was described in HRS cells in classical Hodgkin’s lymphoma." (PMID 38203606, 2023).
Insulin resistance (2 papers, 2017 to 2020). Increased resistance towards insulin, that is, diminished effectiveness of insulin in reducing blood glucose levels. "Indirectly, this theory is supported by dramatically reduced Insulin receptor transcripts and increased transcription of Insulin-like growth factor 1 (IGF-1) in CXCR5-deficient RPE cells suggestive of insulin resistance." (PMID 32492870, 2020). "Dysregulation of CD4+CXCR5+ T cells and production of excessive proinflammatory cytokines may play an important part in the mechanism of chronic low-grade inflammation of insulin resistance." (PMID 28926600, 2017).
ischemic stroke (2 papers, 2020 to 2024). A stroke disorder caused by obstruction of blood flow to the brain, due to thrombotic (local blood clot formation) or embolic (due to a blood clot or other material traveling from another site) event. "However, common variations of CXCR5 (50 kb) were found in the British biological bank cohort; the allele mutations of rs187248852 and rs73575424 are related to the pathogenesis of ischemic stroke and myocardial infarction, respectively." (PMID 33052139, 2020). "Therefore, this study uncovers an important role of CXCL13 expressed on inflamed cerebral vessels in recruiting IL-21-producing TFH cells via CXCR5 to produce neuroinflammation and subsequent neuronal death in ischemic stroke." (PMID 39472796, 2024).
kidney damage (2 papers, 2022 to 2025). "We therefore expected to seek a serological assessment for early indication of kidney damage in SLE patients by evaluating the diagnostic efficacy of CXCL13 and its regulated CXCR5+ T cells in LN." (PMID 41164191, 2025). "An increase in B cells’ CXCR5 expression has been demonstrated when high levels of serum CXCL13 are detected in patients with SLE and nephropathy." (PMID 35663936, 2022).
liver disease (2 papers, 2016 to 2020). "Collectively, in patients with chronic HBV infection, the frequencies of blood CXCR5+CD4+ T cell and B cells were associated with liver disease activity." (PMID 27612199, 2016). "However, experimental models that mimic the unique immunological characteristics upon HBV and HCV infection as well as the development of late stage liver diseases, would greatly facilitate our understanding of CXCR5+ CD8+ T cells for the treatment of infected patients." (PMID 33613516, 2020).
mantle cell lymphoma (2 papers, 2021). Mantle cell lymphoma is a rare form of malignant non-Hodgkin lymphoma affecting B lymphocytes in the lymph nodes in a region called the ``mantle zone''. "B-NHL with nodal lodgings, such as follicular lymphoma (FL), DLBCL, mantle cell lymphoma (MCL), and CLL recapitulate the conserved lymphoid dissemination pattern associated with CXCR5 expression." (PMID 33431832, 2021). "CXCR5 is overexpressed in mantle cell lymphoma (MCL), where it mediates MCL-stromal cell adhesion and drug resistance." (PMID 34947813, 2021).
nasal polyps (2 papers, 2019 to 2024). "CXCR5+TIM-3-PD-1+ CD8+ T cell levels in the nasal polyps of patients with CRS were negatively correlated with the patients’ Lund-Mackay scores." (PMID 38426098, 2024). "Between the two types of nasal tissues in our patients with CRS, CXCR5+TIM-3-PD-1+ cell levels were significantly higher in the paranasal sinus mucosa than in nasal polyps, especially among the CD8+ subpopulation (p=0.046)." (PMID 38426098, 2024). "Our correlation analysis results demonstrated that the percentage (r=-0.564, p=0.045) and number (r=-0.643, p=0.020) of CXCR5+TIM-3-PD-1+ CD8+ T cells in the nasal polyps of patients with CRS were negatively correlated with the LM score, which indicates the severity of disease." (PMID 38426098, 2024). "CXCR5+ CD8 T cells in human nasal polyps that localize to B cells promote inflammatory damage." (PMID 31275308, 2019). "The percentage of CXCR5+ cells among CD8+ T cells was significantly increased in the paranasal sinus mucosa (p=0.018) and nasal polyps (p=0.0079) of patients with CRS than that in healthy controls." (PMID 38426098, 2024). "In addition, a significant positive correlation was noted between CXCR5+TIM-3-PD-1+ CD8+ T cell counts and proportions in paranasal sinus mucosa and nasal polyps from the same patient (percentage: r=0.748, p=0.033; number: r=0.970, p=0.0001)." (PMID 38426098, 2024). "The proportion of CXCR5+TIM-3-PD-1+ cells among both CD8+ and CD4+ T cells was significantly elevated in the paranasal sinus mucosa (CD8+: p=0.0027; CD4+: p=0.024); and in the nasal polyps (CD8+: p=0.042; CD4+: p=0.039); of patients with CRS than the proportion in healthy controls." (PMID 38426098, 2024).
pancreatic ductal adenocarcinoma (2 papers, 2024 to 2025). An infiltrating adenocarcinoma that arises from the epithelial cells of the pancreas. "Furthermore, CXCL13 increases the expression of EVT4 in pancreatic ductal adenocarcinoma (PDAC), and EVT4 promotes PDAC invasion and metastasis by binding to CXCR5 on the tumor cell surface." (PMID 40406143, 2025).
parasite infection (2 papers, 2025 to 2026). "Expression of CXCR5 and production of IL-4 are also not able to discriminate between Th2 and Tfh cells under parasite infection." (PMID 40391228, 2025).
primary biliary cholangitis (2 papers, 2020 to 2024). Primary biliary cholangitis (PBC) is a chronic and slowly progressive cholestatic liver disease of autoimmune etiology characterized by injury of the intrahepatic bile ducts that may eventually lead to liver failure. "In patients with primary biliary cholangitis (PBC), the levels of CD4+CXCR5+CD127loCD25hi Tfr cells, as well as CCR7hiPD-1lo central memory Tfr cells, are dramatically decreased, whereas those of CCR7loPD-1hi effector memory Tfr cells are increased." (PMID 32676074, 2020).
Salmonella Infections (2 papers, 2017 to 2025). Infections with bacteria of the genus SALMONELLA. "We first noticed this in the response to Salmonella infection where there is a rapid and significant induction of CXCR5+ PD1+ T cells (Tfh-like cells) concomitant with an appearance of activated T cells in B cell follicles." (PMID 28503175, 2017). "Cluster 5 was defined by the expression of genes like Tox, Cxcr5, and Pdcd1, consistent with T follicular helper-like cells, which are typically localized in colonic patches or isolated lymphoid follicles and regulate IgA production during Salmonella infection." (PMID 40924026, 2025).
Schistosomiasis japonica (2 papers, 2015 to 2022). Schistosomiasis caused by Schistosoma japonicum. "Therefore, PD-1+CXCR5+ Tfh cells and Tfr cells in the spleen might play an important role in schistosomiasis japonica, and NS398 will mitigate their effects." (PMID 35461268, 2022). "Next, we compared the frequencies of total peripheral memory Tfh cells (CXCR5+CD45RA-CD4+ T cells) and activated peripheral memory Tfh cells (PD-1+ICOS+Tfh cells) among CD4+ T or total peripheral memory Tfh cells in 50 patients with schistosomiasis japonica to 50 healthy controls." (PMID 26284362, 2015).
Thrombocytopenia (2 papers, 2022 to 2025). A reduction in the number of circulating thrombocytes. "The latest research has confirmed that the expansion of Tfh cells correlates with the severity of ITP, which also explains why circulating CXCR5+γδ T cells are closely related to the degree of thrombocytopenia in children with nITP." (PMID 40861056, 2025). "However, limited data are available on the roles of CXCL13 and the circulating CXCR5+ TFHs in patients with thrombocytopenia." (PMID 35450072, 2022). "Intriguingly, we observed significant elevation of circulating CXCR5+ TFHs and plasma CXCL13 in thrombocytopenia cohort." (PMID 35450072, 2022).
uveitis (2 papers, 2018 to 2025). An inflammatory process affecting a part of or the entire uvea. "During uveitis flares, marked by retinal vasculitis and tattoo inflammation, CXCR5 down‐regulation on B and cTfh cells was prominent." (PMID 40469525, 2025). "Finally, we observed a significant decrease in CD4+ Tm CD27+CXCR5+ cells (i.e., follicular T helper cells) in uveitis patients." (PMID 30429855, 2018).
vitiligo (2 papers, 2016 to 2022). Generalized well circumscribed patches of leukoderma that are generally distributed over symmetric body locations and is due to autoimmune destruction of melanocytes. "Association analyses identified that rs638893 at 11q23.3 is associated with vitiligo in the Chinese Han population, and rs638893 is located in an intergenic region between CXCR5 and DDX6." (PMID 26870082, 2016). "Rs638893 located in an intergenic region between DDX6 and CXCR5 is associated with vitiligo." (PMID 26870082, 2016).
age (1 paper, 2017). A temporal measurement of the time period elapsed since an identifiable point in the life cycle of an organism. "In conclusion, our findings suggest that Cxcr5 itself may protect RPE and retinal cells from degeneration during aging and, therefore, its loss may be implicated in age-related pathologies, such as AMD." (PMID 28282423, 2017).
allergic contact dermatitis (1 paper, 2018). An inflammatory skin condition caused by an immune response to direct contact between the skin and an allergen. "The overexpression of C-X-C motif chemokine receptor 5 (CXCR5) is known to intensify the immunomodulatory effects of MSCs, and it decreases allergic contact dermatitis (ACD)." (PMID 30459600, 2018).
allergies (1 paper, 2023). "Regarding regulatory CD4+ T cells, the severity of allergic reactions has been associated with functional damage of allergen-specific Treg cells (CXCR5-FoxP3+IL-10+), Tr-1 (CXCR5-FoxP3-IL-10+) and, mainly in IgE-mediated disorders, TFR (CXCR5+FoxP3+IL-10+)." (PMID 37954580, 2023). "As well as inducing the Th2/TFH2/TFH13 axis, the severity of IgE-mediated allergies has been associated with functional impairment of non-follicular [Treg (CXR5-FoxP3+IL-10+) and Tr-1 (CXCR5-FoxP3-IL-10+)] and follicular [TFR (CXCR5+ FoxP3+IL-10+)] regulatory CD4+ T cells." (PMID 37954580, 2023).
aneurysm (1 paper, 2022). Bulging or ballooning in an area of an artery secondary to arterial wall weakening. "The number of CXCR5 expressing Vδ2+ T cells was significantly increased in aneurysm tissue compared to normal aorta or PBMCs from patients with aneurysm." (PMID 36275758, 2022).
arteriosclerosis (1 paper, 2020). A vascular disorder characterized by thickening and hardening of the walls of the arteries. "In coincubated B cells, the expression of IL-6 and IFN - γ also increased significantly, which may be the possible mechanism of CXCR5-induced arteriosclerosis." (PMID 33052139, 2020).
Atrophy (1 paper, 2017). Any weakening or degeneration, especially through lack of use. "17-month-old Cxcr5-/- mice were further analyzed for RPE atrophy." (PMID 28282423, 2017).
autoimmune myocarditis (1 paper, 2025). Autoimmune myocarditis is an autoimmune disease that affects the heart. "In autoimmune myocarditis mice models, increased mRNA and protein expression of CXCR5 and CXCL13 were found in myocardial tissue." (PMID 40705171, 2025).
autoimmune neuropathy (1 paper, 2024). An autoimmune form of peripheral neuropathy. "In an adoptive transfer model of autoimmune neuropathy, we found that 79-6 treatment was accompanied by a decrease in the frequency of nerve-infiltrating Tph (CD4+ICOS+CXCR5–PD-1+CXCR6+) cells compared with vehicle treatment." (PMID 39087473, 2024).
blastoma (1 paper, 2017). A malignant neoplasm composed of undifferentiated cells. "We then analyzed the expression of CXCR5 on peripheral blood γδT cells from NB patients, other blastoma patients and healthy controls." (PMID 28687069, 2017).
brucellosis (1 paper, 2024). Brucellosis is a bacterial infection that spreads from animals to people via unpasteurized dairy products or by exposure to contaminated animal products or infected animals. "We found that NK cells, especially for NK_Naive, NK_Memory and NK_CD56(dim), in brucellosis patients potentially underwent migration, with several migration‐related genes highly expressed like CCL4, CXCR5, CCL18, CXCL2, and so forth." (PMID 39135683, 2024).
Candida infection (1 paper, 2012). "Of the chemoattractant mediators, several chemokines (Ccl25, Ccl27, Ccl28) and chemokine receptors (Ccr9, Ccr10, Cxcr5, Cxcr6, Cxcr7) associated with adaptive immunity were not induced after Candida infection." (PMID 22916017, 2012).
cervical cancer (1 paper, 2022). A primary or metastatic malignant neoplasm involving the cervix. "Chemokines CXCL19 and chemokine receptors CXCR5 mediate immune cell trafficking into the tumour micro environment based on the DNA methylation of ERBB3 in cervical cancer." (PMID 35581263, 2022).
chlamydial infection (1 paper, 2012). "Thus, in mice and humans the inflammation associated with CXCR5 and CCR5 function may predispose to development of complications of chlamydial infection, such as tubal factor infertility." (PMID 23189125, 2012).
cognitive decline (1 paper, 2020). "CXCL13 and CXCR5 are involved in neurodegeneration and cognitive decline, which are related to a deficit in hippocampal neurogenesis." (PMID 33161894, 2020).
colonic adenoma (1 paper, 2024). "In contrast, CCR2 and CXCR5 were significantly downregulated during the colonic adenoma stage, with CCR2 (Log2FC = −1.02 ± 0.79) and CXCR5 (Log2FC = −1.42 ± 0.57)." (PMID 39409185, 2024).
cutaneous leishmaniasis (1 paper, 2023). Leishmaniasis affecting the skin. "In summary, we identified a novel, less-differentiated CXCR5+ Tex subset in experimental cutaneous leishmaniasis caused by L. mexicana." (PMID 37691941, 2023).
cutaneous malignant melanoma (1 paper, 2023). "These aspects of the CXCL13/CXCR5-associated immune axis are highlighted in this review, which focuses on cutaneous malignant melanoma." (PMID 36836910, 2023). "Specifically, we propose that the CXCR5/CXCL13-axis may represent an additional target for anti-PD-1 therapy in cutaneous melanoma, that is relevant for treatment outcome as well as a potential source of predictive therapeutic biomarkers." (PMID 36836910, 2023).
depression (1 paper, 2014). "Interestingly, these data suggest a non-significant trend toward an anhedonia-like phenotype of CXCR5 deficient mice - the opposite of what would be expected if depression-like behaviours were associated with impaired neurogenesis." (PMID 24528805, 2014).
diabetic nephropathy (1 paper, 2025). "Changes in CXCR5 expression reported in diabetic nephropathy." (PMID 40852718, 2025).
diabetic retinopathy (1 paper, 2020). "However, at the setting of diabetic retinopathy, many PD-1+CXCR5+ CD4+ Tfh cells with round shape accumulated in the diabetic retina." (PMID 32226551, 2020). "The PD-1+CXCR5+CD4+ GC Tfh cells were expanded markedly both 6 weeks and 12 weeks after STZ injection in the spleen of DR mice, indicating that excess generation and maintaining of Tfh cells were accompanied with the progression of diabetic retinopathy." (PMID 32226551, 2020).
DiGeorge syndrome (1 paper, 2018). "We observed a strongly increased expression of PD1 on cTFHs, and to lesser extent also CXCR5− memory CD4+ T cells, in infants in both DiGeorge syndrome patients and healthy controls." (PMID 30083170, 2018). "The population of CXCR5+ memory CD4+ T cells (cTFHs) was significantly expanded in patients with DiGeorge syndrome, but only healthy controls and not DiGeorge syndrome patients showed gradual increase of CXCR5 expression on cTFHs with age." (PMID 30083170, 2018). "We observed a significant decrease of PD1 expression on cTFHs (linear regression, p = 0.01, R2 = 0.78), but not CXCR5− memory CD4+ T cells or CD4− T cells in the first 5 years of life in patients with DiGeorge syndrome." (PMID 30083170, 2018). "PD1 expression further decreases later in life on cTFHs (linear regression, p = 0.04, R2 = 0.37), but not CXCR5− memory CD4+ T cells and CD4− T cells in DiGeorge syndrome." (PMID 30083170, 2018). "We then show a much slower and gradual increase of PD1 expression in CXCR5− memory CD4+ T cells and CD4− T cells in healthy controls, but not DiGeorge syndrome patients, in older childhood and adolescence." (PMID 30083170, 2018).
dry mouth (1 paper, 2022). "Co-expression levels of PD-1, CXCR5, CD4, CCR2, and CCR5 in the salivary gland specimens from patients with pSS and patients with dry mouth and eyes but normal pathology were also analyzed." (PMID 35755031, 2022).
gastritis (1 paper, 2021). Inflammation of the stomach. "Here we identified a subset of tissue-resident CXCR5-BTLA-PD-1hi TFH-like cells with IL-21 production in the mucosal tissue of H. pylori-positive gastritis patients." (PMID 34589088, 2021).
geographic atrophy (1 paper, 2019). "A total of two out of 10 aged CXCR5−/− female mice indicated abnormalities consistent with the geographic atrophy (GA) when examined by fundus images with presence of a large white spot in visible light, with autofluorescence at 488 nm excitation and H&E staining of the same eye." (PMID 31474986, 2019).
glioblastoma (1 paper, 2023). The most malignant astrocytic tumor (WHO grade IV). "In our study, we screened primary glioblastoma data from the TCGA and CGGA databases and found that only CXCR3, CXCR4, and CXCR5 mRNA expression differed significantly between the two databases, suggesting that these members may be more closely linked in the onset and progression of GBM." (PMID 37626511, 2023).
Hashimoto thyroiditis (1 paper, 2022). An autoimmune disorder caused by the production of autoantibodies against thyroid tissue. "The percentage of CXCR5 + circulating TFH cells was elevated in patients with Hashimoto’s thyroiditis compared with controls, as were the percentages of PD-1+ TFH cells." (PMID 35672305, 2022).
heart failure (1 paper, 2025). Inability of the heart to pump blood at an adequate rate to meet tissue metabolic requirements. "The chemokine CXCL13 and its receptor CXCR5 play a significant role in cardiac remodeling, and their expression is markedly increased in experimental models of heart failure." (PMID 40650190, 2025). "It has been demonstrated that reduced CXCR5 expression may lead to increased myocardial degradation and accelerated cardiac degeneration, ultimately resulting in heart failure." (PMID 40650190, 2025).
hemophilia A (1 paper, 2025). The most common form of hemophilia characterized by spontaneous or prolonged hemorrhages due to factor VIII deficiency. "In this study, we generated human and murine CXCR5 co-expressing engineered receptor Tregs and tested them in preclinical mouse models of allo-immunity and hemophilia A, respectively." (PMID 40666520, 2025). "Similarly, FVIII TRuCe CXCR5 Treg demonstrated increased in vivo persistence and suppressive capacity in a murine model of hemophilia A." (PMID 40666520, 2025). "Similarly, we engineered murine CXCR5 co-expressing FVIII TRuCε Tregs to suppress FVIII specific ADA responses in a murine model of hemophilia A (HA)." (PMID 40666520, 2025). "Additionally, we engineered a murine CXCR5 co-expressing clotting factor VIII (FVIII) specific T cell receptor fusion construct epsilon (FVIII TRuCe CXCR5) Treg to suppress anti-drug antibody development in a model of FVIII protein replacement therapy for hemophilia A." (PMID 40666520, 2025).
hepatitis B (1 paper, 2018). "We then analyzed baseline CXCR5+ memory T cell compartments according to subsequent serological response to hepatitis B vaccine." (PMID 30303980, 2018).